ZNF491 (zinc finger protein 491)
Description:
May be involved in transcriptional regulation.
Synonyms: FLJ34791
Tractability: PROTAC: ubiquitination databases record sites on it.
Gene: Protein-coding gene on chromosome 19 (11,797,642 to 11,809,622, forward strand). Ensembl gene ENSG00000177599.
Subcellular location: Nucleus
Gene Ontology:
Molecular function: protein binding; DNA-binding transcription factor activity, RNA polymerase II-specific; RNA polymerase II transcription regulatory region sequence-specific DNA binding
Biological process: regulation of transcription by RNA polymerase II
Cellular component: nucleus
Genetic constraint (gnomAD): Loss-of-function variants: 22 observed, 35.79 expected, observed/expected ratio (o/e) 0.61, 90% interval 0.44 to 0.88. The upper end of that interval is the gene's LOEUF score, 0.88, which puts it in group 3 of 6, group 1 being the genes least tolerant of losing a copy. Missense variants: 555 observed, 554 expected, observed/expected ratio (o/e) 1, 90% interval 0.93 to 1.08. Synonymous variants: 147 observed, 181.91 expected, observed/expected ratio (o/e) 0.81, 90% interval 0.71 to 0.93.
Homologues: Orthologues: mouse Zfp78 (28% identical), Drosophila melanogaster CG3281 (19% identical), Drosophila melanogaster Phs (17% identical), Drosophila melanogaster CG2712 (16% identical). Paralogues in human: ZNF69 (63% identical), ZNF439 (61% identical), ZNF440 (61% identical), ZNF20 (54% identical), ZNF763 (46% identical), ZNF555 (43% identical), ZNF560 (36% identical), ZNF266 (35% identical), ZNF778 (35% identical), ZNF599 (34% identical), ZNF77 (34% identical), ZNF596 (32% identical), and 50 more.
Diseases named in the same sentence as ZNF491 in open-access papers:
ZNF491 is named in the same sentence as 1 disease in open-access papers, as found by Europe PMC text mining. Sharing a sentence is not in itself a finding about the gene and the disease. The quoted sentences say what the papers report.
tumor (1 paper, 2022). "From the perspective of tumor-infiltrating cells in the TME, the results from TIMER showed that the ZNF491 expression level was significantly positively related to the infiltration of the majority of immune cell types in the TME in PRAD, KIRC, and LIHC." (PMID 36578929, 2022).